CRP (C-reactive protein)
Diseases named in the same sentence as CRP in open-access papers (continued):
Sharing a sentence is not in itself a finding about the gene and the disease.
Sepsis (continued). "The periodic monitoring of the MHLA-DR expression together with CRP and sepsis index may help to identify patients in the ICU at increased risk of developing sepsis." (PMID 37509475, 2023). "However, these same studies have also found NGAL to increase with sepsis, and elevated serum CRP correlates with increased serum and urinary NGAL." (PMID 38078317, 2023). "It is recognized that CRP is an acute inflammatory marker in the acute-phase reaction of sepsis." (PMID 37238265, 2023). "It was also shown that the MD may reduce the probability of sepsis and lung infections, as well as inflammation, as indicated by a reduction in c-reactive protein (CRP) and proinflammatory cytokines." (PMID 37836406, 2023). "For the development of sepsis-associated organ dysfunction according to the sepsis-3 definition, the order of significant univariate results was SOFA, body temperature, gender, vasopressor therapy, shock index, respiratory rate, and CRP." (PMID 37628779, 2023). "Notably, plasma PCSK9 positively correlated with the leukocyte count, procalcitonin, and CRP in patients with SIRS/sepsis and liver cirrhosis." (PMID 37515197, 2023). "Fourteen patients with CRP at diagnosis (12%) had marked elevation (>100 mg/L); 11 of these patients had hand cellulitis, including 7 with systemic inflammatory responses consistent with sepsis." (PMID 35130740, 2023). "The aim of this prospective observational study was to evaluate the predictive value of the biomarkers mid-regional pro-adrenomedullin (MR-proADM), procalcitonin (PCT), C-reactive protein (CRP), and lactate for 28-day mortality in patients with sepsis, and patients with a SOFA score ≤6." (PMID 37626646, 2023). "We showed that the repeatedly measured HRG, P-SEP, and SOFA scores, and not PCT and CRP, were significantly associated with mortality in the acute phase of sepsis." (PMID 36989333, 2023). "Hence, PCT is compared to CRP as a part of the official guideline for diagnosing sepsis and infection in adult medicine." (PMID 35615626, 2022). "Furthermore, miR-15a can allow for a distinction between sepsis and SIRS, showing higher expression in SIRS and having a higher AUC for sepsis diagnosis than do C-reactive protein and PCT." (PMID 35305556, 2022). "In the non-sepsis group, the levels of CRP correlated with 28-day mortality." (PMID 36050405, 2022). "PCT and CRP can predict sepsis; however, their role in postoperative patients is less explored." (PMID 36475186, 2022). "The primary purpose of the study was to determine whether ambulation ability with albumin and C-reactive protein are predictive of 28-day mortality of elderly patients with sepsis." (PMID 35962331, 2022). "As a result, PCT and CRP can be used to diagnose sepsis as a preliminary infection index." (PMID 36189371, 2022). "The AUC of CRP to predict sepsis was 0.799, all the other biomarkers had AUC’s lower than that." (PMID 35550043, 2022). "Most infants had more than one significant documented problem: 126 had neonatal sepsis (with either a significant rise in inflammatory markers (CRP > 10) or required antibiotics for > 5 days), 7 patients had a positive blood culture, and 25 infants were found to have congenital pneumonia." (PMID 34618229, 2022). "As for the nonspecific biomarker, C-reactive protein, our data showed that high values (≥ 8 mg/dL) on the first day of sepsis were associated with a high probability of developing SAE." (PMID 35739230, 2022). "CRP levels are raised in inflammatory conditions including sepsis." (PMID 35633256, 2022). "The literature often promotes the superiority of PCT over CRP for predicting sepsis after trauma." (PMID 36816532, 2022). "We used pSOFA criteria, which is adapted from Sepsis-3 SOFA score for pediatric patients, and it could explain why the specificity of PCT in diagnosing sepsis was even lower than CRP’s." (PMID 35550043, 2022).
Sepsis (continued). "PCT is an earlier and comparative biomarker of sepsis in comparison to CRP in the early phase of neonatal sepsis, while a rising PCT level on subsequent days can prognosticate the severity of sepsis or risk of mortality with more than 95% sensitivity, specificity, and accuracy in a surgical neonate." (PMID 36158418, 2022). "Of these, PCT and CRP are widely studied biomarkers in sepsis." (PMID 36158418, 2022). "Therefore, a number of serum biomarkers have been proposed to predict septic shock in sepsis patients such as C-reactive protein (CRP), cytokines (IL-1, IL-6, IL-10 and TNF-α), chemokines (IL-8, MCP-1, G-CSF) and procalcitonin." (PMID 36874368, 2022). "In addition, CAR has recently been considered a more useful indicator of sepsis than CRP or ALB alone in adults." (PMID 35873709, 2022). "Enrolled were all NICU patients, for whom CRP was obtained as part of a sepsis workup." (PMID 36517750, 2022). "While the majority of the tests were completed in the context of respiratory symptoms, our data demonstrate some of the other uses for which clinicians elected to undertake CRP testing when given the autonomy to do so, including sepsis, abdominal pain, and knee pain." (PMID 35892398, 2022). "In addition, higher mean CRP concentrations were found in dogs with SIRS or sepsis (165 ± 82 μg/mL) than in those with localized inflammation (108 ± 70 μg/mL)." (PMID 36290272, 2022). "In addition, in the early stage of sepsis, the liver will prioritize the synthesis of acute phase proteins such as CRP over ALB." (PMID 35109818, 2022). "However, CRP is documented to be raised in post-operative patients, which jeopardises the value of CRP attributed to sepsis alone." (PMID 36158418, 2022). "When examining the maximal CRP concentration within 72 h of the time of the sepsis workup (clinical sepsis), no clear associations with CP sepsis, either EOS or LOS, were found." (PMID 36233706, 2022). "Bio-ADM exceeds the prognostic properties of routine biomarkers as lactate, CRP and creatinine and may be of clinical importance for triage of sepsis patients in the ED." (PMID 35482727, 2022). "Second, an elevated serum ALP might reflect inflammation, because increased ALP levels have been reported in sepsis or with elevated C-reactive protein." (PMID 35683370, 2022). "At the time of sepsis onset, CRP was more than 1 mg/dL in 46 (45.5%) sepsis episodes." (PMID 36360371, 2022). "PCT has been documented to be a more accurate and promising marker for sepsis with respect to CRP." (PMID 36158418, 2022). "As the clinicians were blinded to the CRP measurements and antimicrobial treatment was initiated due to the sepsis criteria of this study or due to neutropenia, this might support the assumption that CRP is not a good prognostic marker in patients with AHDS." (PMID 36713872, 2022). "Considering the improvements of CRP and lactic acid, it is reasonable to interpret that continuous infusion is advantageous for resolving infection by obtaining an appropriate concentration of antibiotics for sepsis patients with pharmacokinetic variations." (PMID 36358163, 2022). "Advantages of CRP as sepsis marker include its broad availability, simplicity, speed, and low cost." (PMID 35345614, 2022). "In addition, a recent study reported that the decrease in level of miR-25 was correlated with the severity of sepsis, with better clinical accuracy for sepsis diagnosis than CRP and PCT levels." (PMID 35056044, 2022). "Although the PHENOMS study represents the largest longitudinal multiple center pediatric sepsis-induced MOF cohort with concomitant CRP and ferritin levels available, it is small compared to adult standards because sepsis occurs 15 times more commonly in adults than in children." (PMID 35526000, 2022). "CRP combined with sFAS showed increase in sensitivity in predicting sepsis (88% vs. 83%)." (PMID 35550043, 2022). "We therefore defined clinical sepsis as a symptomatic episode with elevated CRP 1–3 days later." (PMID 36233706, 2022).
Sepsis (continued). "In addition, the multivariate analysis showed that age, sepsis, surgery, CRP, albumin level, lymphocyte count, Hb level, APACHE II score, duration of MV, and RBC and PLT transfusion were significantly associated with PIICS." (PMID 35022421, 2022). "C-reactive protein (CRP) also plays an irreplaceable role in the pathogenesis of Sepsis." (PMID 35463634, 2022). "CRP is the most widely used biomarker in laboratory settings for identifying neonatal sepsis." (PMID 35449688, 2022). "Procalcitonin can be used as a marker of severity of systemic inflammation due to a bacterial infection and may be more specific than CRP in diagnosing and monitoring sepsis." (PMID 35829905, 2022). "With a cut-off of 230 in mean fluorescence intensity (MFI), and particularly if combined with abnormal CRP values, a probability for sepsis of 92% was described; importantly, if values were both normal, sepsis could be excluded with 99% confidence." (PMID 36676685, 2022). "CRP has been studied for its prognostic efficacy for sepsis." (PMID 35907785, 2022). "Previous studies have found high high-Sensitive C-Reactive protein/albumin ratio and low AGR could both serve as an independent risk factor of sepsis after PNL and fURS respectively." (PMID 35495750, 2022). "However, the early recognition of sepsis is still hampered by ambiguous clinical signs and the limited accuracy of laboratory biomarkers e.g. the C-Reactive Protein, Procalcitonin and Lactic acid." (PMID 36376821, 2022). "Furthermore, MDW as a screening indicator is effective for assessment of sepsis in conjunction with CRP and PCT as confirmatory indicators, and MDW is especially useful for sepsis assessment in patients with a suspected infection." (PMID 36538555, 2022). "Furthermore, in addition to traditional biomarkers of infection/sepsis, such as procalcitonin and C-reactive protein (CRP), a soluble CD4 subtype, presepsin, has emerged." (PMID 35778478, 2022). "Furthermore, studies have shown that procalcitonin is superior to other acute-phase proteins (ESR and CRP) in predicting infection and sepsis." (PMID 39604183, 2022). "When ADM was correlated with the C-reactive protein levels in these patients, it could identify sepsis or cancer patients." (PMID 36004964, 2022). "Mean CRP was 8.3 mg/dl, and 27 (18%) patients were diagnosed with sepsis." (PMID 39845592, 2022). "Subsequent studies verified the utility of MDW in the diagnosis of early sepsis and recent studies have compared the MDW in combination with the white blood cell (WBC) count against such biomarkers as the CRP or PCT to show that the ability of MDW to diagnose sepsis was either similar or better." (PMID 36538555, 2022). "As expected, significant differences were seen in key laboratory values such as C-reactive protein (21.1 [15.2–28.9] mg/dl in sepsis vs. 0.2 [0.0–0.8] in controls) and levels of creatinine clearance (19 ml/min/1.73m2 in sepsis vs. 62 ml/min/1.73m2 in controls)." (PMID 35085240, 2022). "This aberrant immune response, comparable to other hyperinflammatory syndromes such as hemophagocytic lymphohistiocytosis and sepsis, is characterized by strikingly elevated levels of inflammatory cytokines (e.g., interleukin[IL]-1, IL-6) and C-reactive protein (CRP)." (PMID 36557676, 2022). "Highly sensitive CRP (hs-CRP) is more sensitive than conventional CRP for diagnosing infant sepsis." (PMID 35449688, 2022). "We found CRP was an independent predictive factor of sepsis for short term mortality." (PMID 35907785, 2022). "Increased CRP is an indicator of inflammation in patients with sepsis." (PMID 35236914, 2022). "BBB disruption in patients deceased from sepsis was found to correlate with elevated CRP levels." (PMID 35049659, 2022). "The increase in PCT and CRP levels during infection exhibits predictable kinetics, appropriate half-life, and high specificity, making them an ideal combination of biomarkers for the diagnosis of sepsis due to bacterial infections." (PMID 35149284, 2022).
Sepsis (continued). "Children with complement variants were less likely to have culture-negative sepsis and had increased odds of hyperferritinemia, thrombocytopenia, and CRP > 10 mg/dl." (PMID 34973142, 2022). "As sepsis in neonates has fulminant developments, CRP-guided antibiotic treatment may be used to reduce the duration of antibiotic exposure stopping antibiotics early." (PMID 35622691, 2022). "All the patients with sepsis showed very high CRP levels followed by d‐dimer, G‐CSF, and IL‐8." (PMID 36176597, 2022). "In patients with sepsis aged 18 years and older, albumin/CRP ratios at admission and discharge were better predictors of 90-day and 180-day mortality after hospitalization compared to albumin or CRP alone." (PMID 35235196, 2022). "Finally, we found a significant correlation between the nadir of SChE activity (lowest value) recorded during ICU stay and the nadir recorded for other biomarkers of sepsis—in particular, with CRP (P < 0.001; r = –0.38) and procalcitonin (P = 0.04; r = –0.17)." (PMID 35895337, 2022). "Many serological biomarkers helpful for sepsis diagnosis and as outcome predictors are routinely employed (i.e., procalcitonin, c-reactive protein, lactate serum level, and cytokines), but they lack specificity, not able to distinguish sepsis from other conditions." (PMID 36611371, 2022). "A meta-analysis including 17 randomized controlled trials suggested that the Xuebijing injection combining with the ulinastatin for the sepsis patients decreased 28-day death, shortened mechanical ventilation duration, lowered procalcitonin levels, and reduced C-reactive protein concentrations." (PMID 36072401, 2022). "In this study, cytokines TNF, IL-6, IL-10, IFN-γ, IL-27, alarmins Hsp72 and Hsp90, and markers associated with inflammation (CRP, procalcitonin, lactate) and stress (glucose) exhibited early-onset induction, which was strongly correlated with an increased TOS/TAC ratio in sepsis." (PMID 35204114, 2022). "uNGAL may be impacted by sepsis as it correlated with C reactive protein (CRP) and clinical severity but also correlated well with AKI." (PMID 35433560, 2022). "However, some others hold the view that CRP is a confounding factor in identifying sepsis in burn patients because the chronic inflammatory response is part of the normal stress response in patients with burn injuries." (PMID 33833617, 2021). "Assuming that the detection of a single CRP+ EV would require an equal amount of labeled antibody, we calculated that in sepsis patients with average plasma CRP levels of approximately 230 mg/L and 5400 CRP+ EVs/μL, the total amount of EV-bound CRP would be equal to 5.6 μg." (PMID 33772103, 2021). "CRP, monocyte and neutrophil L-selectin were again the only three significant predictors of sepsis, with respective AUCs of 0.79 2 (95%CI 0.657–0.928) p = 0.0007, 0.720 (95%CI 0.564–0.876) p = 0.011 and 0.731 (95%CI 0.589–0.873) p = 0.008, which were not significantly different from one another." (PMID 34065206, 2021). "Here, we characterized the interaction of pro-coagulant EVs from sepsis patients with CRP, which, apart from being a marker of inflammation, can actively mediate tissue damage following structural changes from its native, pentameric state into its monomeric form." (PMID 33772103, 2021). "C-reactive protein (CRP) is a commonly used serum biomarker for detecting sepsis in neonates." (PMID 33673378, 2021). "the patient has clinical symptoms of sepsis and 2A) a common commensal is identified in two separate blood cultures or 2B) a common commensal is identified by one blood culture and C-reactive protein level is above 10 mg/L in the first 36 h following blood culture collection." (PMID 33546759, 2021). "Furthermore, procalcitonin (an established biomarker for sepsis) and progranulin were significantly different, whereas interleukin-6 and C-reactive-protein were comparable between these two groups." (PMID 34956213, 2021).
Sepsis (continued). "A study found Serum sTREM-1, PCT, and CRP levels each have a role in the early diagnosis of sepsis." (PMID 34513755, 2021). "Numerous studies have demonstrated a close correlation between CRP and sepsis." (PMID 33833617, 2021). "Sepsis at the time point of sampling was indicated by a threshold of >15 μg/mL CRP in serum." (PMID 33673378, 2021). "Elevated CRP levels are related to the severity of sepsis and the prognosis of the disease outcome." (PMID 34436070, 2021). "On admission, CRP and CRP/Albumin ratio were higher among patients admitted to ICU with sepsis." (PMID 35199783, 2021). "While the diagnostic accuracy of PSP, CRP and PCT for sepsis were similar in this cohort, serial PSP measurement demonstrated an increase of this marker the days preceding the onset of signs necessary to clinical diagnose sepsis." (PMID 33879189, 2021). "To confirm the development of sepsis, we quantified the concentration of CRP in the serum." (PMID 34421366, 2021). "Since CRP also showed good predictability in the single-predictor PDP and was a significant factor along with IG% in the ROC and logistic regression analyses, we used a multi-predictor PDP to show the effect of the interaction between CRP and IG% on sepsis predictability." (PMID 34915849, 2021). "Here, new time-related insights on the C-reactive protein (CRP) and sepsis are presented." (PMID 34884171, 2021). "As already discussed, the CRP is the most important component of the sepsis screen." (PMID 34912626, 2021). "However, the other group used high-sensitive CRP in asymptomatic subjects, whereas we used conventional CRP in ICU sepsis patients." (PMID 35071235, 2021). "The direct and acute effect of high CRP concentrations on blood pressure gives a first hint, why critically ill patients, suffering from e.g., sepsis or acute pancreatitis, can develop hardly controllable hemodynamic variables with preceding elevated CRP levels." (PMID 33679775, 2021). "The CRP/Alb ratio was initially studied as a prognostic indicator of sepsis." (PMID 34900028, 2021). "In addition, in the sepsis cohort, an increase of inflammatory markers, such as CRP, PCT, and ferritin, was more pronounced than in participants with non-sepsis." (PMID 34805199, 2021). "Therefore, with the deep understanding of the clinical significance of CRP in the diagnosis, treatment, and prognosis of sepsis in SARS-CoV-2 infection is helpful to the early rational use of phased antibiotics." (PMID 34447386, 2021). "Furthermore, the ICU mortality rates of patients with sepsis during an ICU stay with CRP concentrations <10, 10–20, 20–30, 30–40, and >40 mg/dL were 20%, 34%, 30.8%, 42.3%, and 39.1%, respectively." (PMID 33606735, 2021). "In the last few years, NPs have been used to detect CRP in sepsis." (PMID 34281552, 2021). "CRP is a well-established marker of inflammation, but it has been considered to be insufficient as a useful biomarker to predict prognosis and microbial patterns in sepsis." (PMID 33810263, 2021). "Other markers, including CRP and PCT, were also analyzed in our study, and their predictive abilities appeared negative, and they failed to forecast progressive bacterial infection in terms of sepsis in early diagnostic settings." (PMID 34722578, 2021). "PCT and CRP levels do not provide statistically significant prediction of 28-day mortality in sepsis patients; however, WRS is significantly associated with 28-day overall mortality among patients with sepsis in intensive care units." (PMID 33926067, 2021). "CRP, an acute-phase reactant, is positively correlated with infection and now serves as a classical biomarker to assist the diagnosis of inflammation-relevant diseases such as sepsis." (PMID 33717630, 2021). "Although many meta-analyses have investigated the diagnostic reliability of PCT and CRP in sepsis and local infection, there is no consensus for proposing a widely accepted cut-off value for these biomarkers." (PMID 34344141, 2021).